CHRNA3 (cholinergic receptor nicotinic alpha 3 subunit)
Diseases named in the same sentence as CHRNA3 in open-access papers (continued):
Sharing a sentence is not in itself a finding about the gene and the disease.
lung carcinoma (continued). "Given the association between the CHRNA3/CHRNA5/CHRNB4 locus and the risk of lung cancer, attempts have been made to elucidate the pathophysiological role of these three genes encoding α3, α5 and β4 nAChR subunits." (PMID 28978081, 2017). "CHRNA3, CHRNA5, and CHRNB4 are subunits of the nicotinic acetylcholine receptor, which contribute to lung cancer risk." (PMID 29207642, 2017). "The region on 15q25 contains the genes CHRNA3, CHRNA5, CHRNB4, AGPHD1, and IREB2, and numerous GWA have shown evidence of association of this region with COPD, emphysema, lung cancer, and smoking intensity." (PMID 26634245, 2015). "Two SNPs (rs1051730 and rs8034191, both with p<1×10−17) with strong LD in the regions of 15q25.1 containing CHRNA3, CHRNA5, and PSMA4 are strongly associated with lung cancer risk among ever smokers." (PMID 25233467, 2014). "Recently, variants in the nAChR genes CHRNA3, CHRNA5, and CHRNB4 have been implicated in nicotine dependence and lung cancer susceptibility." (PMID 24062692, 2013). "CHRNA3/5 (15q25) was reported to be associated with both COPD and lung cancer through its effects on both smoking exposure and COPD." (PMID 23870182, 2013). "In lung cancer, we have detected the expression of several nAChR subunit genes, in particular CHRNA3, CHRNA5, and CHRNB4." (PMID 24062692, 2013). "This pathway contains the CHRNA3-CHRNA5-CHRNB4 gene cluster at 15q25, where GWAS have identified several SNPs associated with lung cancer risk." (PMID 22363742, 2012). "Both the rs169968 SNP (CHRNA3/5 gene on the Chr 15q25 locus) and the rs1052486 SNP (BAT3 gene on the Chr 6p21 locus) appear to confer susceptibility to lung cancer, but the latter only in conjunction with COPD (G2)." (PMID 21304900, 2011). "The locus on chromosome 15q25.1 contains three genes that encode nicotinic acetylcholine receptor (nAChR) subunits (CHRNA3, CHRNA5, CHRNB4) whose involvement in tobacco addiction was suggested from studies conducted on larger lung cancer populations." (PMID 21966413, 2011). "Given their roles as nicotine receptors, CHRNA3 and CHRNA5 may explain associations with smoking‐related diseases like COPD and lung cancer." (PMID 41377765, 2025). "In total, for the neuroactive ligand receptor interaction pathway, CHRNA3 rs1051730 and CHRNB4 rs6495309 reached the criterion and were included for further analysis of the independent association and combined effects of SNPs on lung cancer risk." (PMID 30104567, 2018). "And CHRNA3 may be of vital importance to small cell lung cancer (SCLC) cell viability and play a direct role in lung cancer susceptibility." (PMID 26831765, 2016). "The CHRNA3 rs1051730 variant has previously been linked to smoking fewer cigarettes and lower risks of lung cancer, although this variant does not influence the chances of starting smoking." (PMID 27015805, 2016). "Importantly, they have also identified downregulation of p63 after knockdown of CHRNA5 or CHRNA3, which offered an explanation for the resistance to apoptosis in CHRNA3 downregulated lung cancers." (PMID 26981122, 2016). "Apart from smoke exposure, genome-wide association studies (GWAS) has provided a strong evidence that tobacco-dependent lung cancer patients had a susceptibility region in chromosome 15q25.1, including some genes (CHRNB4, CHRNA3, and CHRNA5) that encode for nicotinic acetylcholine receptors." (PMID 25280560, 2014). "The significant SNP in the present study, rs8042374, localizes to intron 4 of CHRNA3; this was first confirmed with increased lung cancer risk in a British GWAS, but was not replicated in another study of ADC among British residents of European ancestry." (PMID 24686516, 2014). "Importantly, several GWAS based on Caucasian populations have consistently identified 15q25 as lung cancer susceptibility region, which contains the nicotinic acetylcholine receptor subunit gene cluster, harboring CHRNA5, CHRNA3 and CHRNA4 genes." (PMID 23469231, 2013).
lung carcinoma (continued). "For instance in lung cancer, it has been shown that the CHRNA3 gene is frequently hypermethylated in lung tumor tissue samples (in comparison with blood control samples) and that this hypermethylation, by inducing gene silencing, results in resistance against nicotine-induced apoptosis." (PMID 23349703, 2013). "Distribution of genotypes in CHRNA3 gene and associations with risk of COPD and lung cancer." (PMID 23056235, 2012). "The association of this pathway with risk is not unexpected as several SNPs at or near the CHRNA3-CHRNA5-CHRNB4 gene cluster are associated with both lung cancer risk and nicotine addiction." (PMID 22363742, 2012). "Therefore, in current study, we investigated the associations between two SNPs (rs1051730 and rs6495309) in the CHRNA3 gene and risk as well as prognosis of COPD and lung cancer in southern and eastern Chinese populations." (PMID 23056235, 2012). "Based on our search strategy, the primary screening produced 40 potentially relevant articles, of which 12 met the inclusion criteria in an attempt to evaluate the association of CHRNA3 gene rs1051730 and/or AGPHD1 gene rs8034191 polymorphisms with lung cancer risk." (PMID 22701590, 2012). "Among these variables, the association of CHRNA3 gene rs1051730 (correlation coefficient: 0.48, P = 0.069) and AGPHD1 gene rs8034191 (correlation coefficient: 0.57, P = 0.043) polymorphisms with lung cancer risk was observed in cases with a high smoking rate under the allelic model." (PMID 22701590, 2012). "While only the nAChR genes on 15q25.1 (CHRNA5, CHRNA3, CHRNB4) have been previously associated with lung cancer risk, there is strong biological rationale to believe that other nAChR genes may influence risk." (PMID 23232035, 2012). "In the chr15q25.1 region spanning the nicotinic receptors CHRNA3 and CHRNA5, we identified multiple SNPs associated with CPD (p<10−3), including rs1051730, which has been associated with nicotine dependence, smoking intensity and lung cancer risk." (PMID 19247474, 2009). "Overexpression of CHRNA3 by ectopic expression induces apoptotic cell death while CHRNA3 knockdown by short hairpin RNA (shRNA) abolishes the cell response to apoptosis-inducing agents in lung cancer, suggesting this gene is important to human cancer cell survival." (PMID 28978081, 2017). "Using a case-control study, we decided to investigate the associations between CHRNA3 rs6495308, CHRNB4 rs11072768, smoking behaviors and lung cancer risk, as well as explore whether the two SNPs have a direct or indirect carcinogenic effect on lung cancer." (PMID 26942719, 2016). "SNPs near the CHRNA3-CHRNA5-CHRNB4 gene cluster showing strong associations with lung cancer risk, are in strong LD, and there is overlap among SNP test statistics assigned to these genes (i.e., the test statistic for the same SNP was assigned to both CHRNA5 and CHRNA3)." (PMID 22363742, 2012). "Cross‐validated SNPs rs16969968/rs12914385, cis‐regulatory hubs for COPD–lung cancer pathogenesis, colocalized with ρ‐HESS‐identified regions, mechanistically linking dysregulation of PSMA4, IREB2, CHRNA3, and CHRNA5 to disease etiology." (PMID 41377765, 2025). "The locus on chromosome 15q25.1, including the nicotinic acetylcholine receptors CHRNA3, CHRNA5 and CHRNB4, showed concordant effect direction between SCZ, lung cancer, and smoking behavior." (PMID 29330379, 2018). "IREB2 is in strong linkage disequilibrium (LD) with nicotine receptor genes (CHRNA3 and 5) and it is this that led IREB2 to be investigated in relation to respiratory conditions such as chronic obstructive pulmonary disease and lung cancer." (PMID 26629341, 2015). "Three different GWAS, published virtually simultaneously, provided the first convincing evidence for an association between heritable genetic variation at the nicotinic acetylcholine receptor CHRNA5/CHRNA3/CHRNB4 locus on chromosome 15q25.1 and lung cancer." (PMID 23820649, 2013).
lung carcinoma (continued). "Two SNPs (rs6495309 and rs1051730) located in nicotinic acetylcholine receptor alpha 3 (CHRNA3) gene were genotyped in 1511 patients with COPD, 1559 lung cancer cases and 1677 controls in southern and eastern Chinese populations." (PMID 23056235, 2012). "The opposite results for CHRNA3 expression in SCLC cell lines and in NSCLC tumors suggests the existence of different regulatory mechanisms for gene expression in these two categories of lung cancer." (PMID 28978081, 2017). "Because knockdown of CHRNA3 and CHRNA5 increased the proliferation, migration and calcium influx of lung cancer cell lines, as a result of compensatory increase of assembly of α7-nAChR on the cytoplasm membrane which had higher permeability to calcium in response to nicotine." (PMID 24621512, 2014). "Our findings demonstrated that CHRNA3 gene rs1051730-A allele and AGPHD1 gene rs8034191-T allele might be risk-conferring factors for the development of lung cancer in Caucasians, but not in East-Asians." (PMID 22701590, 2012). "Overall results demonstrated that CHRNA3 gene rs1051730-A allele and AGPHD1 gene rs8034191-T allele might be risk-conferring factors for the development of lung cancer in Caucasians, but not in East-Asians." (PMID 22701590, 2012). "Taken together, we have expanded previously individual studies by providing the convincing evidence that CHRNA3 gene rs1051730-A allele and AGPHD1 gene rs8034191-T allele might be risk-conferring factors for the development of lung cancer in Caucasians, but not in East-Asians." (PMID 22701590, 2012). "Interestingly, they found CHRNA3, but not CHRNA5, is often hypermethylated and downregulated in cancer tissues, whereas a 30-fold upregulation of CHRNA5 expression is observed in lung cancers compared with the normal lung." (PMID 26981122, 2016).
nicotine dependence (60 papers, 2009 to 2025). Physical and psychological dependence on nicotine. "Variants in the CHRNA3/5 cluster on chromosome 15q25 have been consistently linked to nicotine dependence and smoking behavior in multiple populations." (PMID 41301874, 2025). "Meanwhile, rs578776 resides within CHRNA3, a gene repeatedly linked to nicotine dependence and autonomic modulation via cholinergic pathways." (PMID 41009356, 2025). "Genetic factors, which are indicated in affecting nicotine dependence, include genetic variants of α3, α4 and α5 subunits of nicotinic receptors, which are encoded by CHRNA3, CHRNA4 and CHRNA5 genes, respectively." (PMID 35222535, 2022). "Some of the previous similar studies reported associations between CHRNA3 rs578776 polymorphism and nicotine dependence in Caucasians." (PMID 35222535, 2022). "The research stated that novel haplotypes G-T-T and G-C-T, though with very low-frequency variants in CHRNA3, were associated with nicotine addiction." (PMID 36078193, 2022). "Using a family-based association test, Li and colleagues found a nominal association rs1317286 and rs8040868 in CHRNA3 with nicotine dependence in the African Americans and combined with European American samples." (PMID 34205269, 2021). "Numerous GWAS have identified the CHRNA5/CHRNA3/CHRNB4 gene cluster as the region harboring the strongest association with nicotine dependence." (PMID 30453884, 2018). "Genome-wide association studies (GWAS) have highlighted the prevailing view that smoking quantity and frequency as a proxy for nicotine dependence is most associated with single nucleotide polymorphisms (SNPs) at the CHRNA5/CHRNA3/CHRNB4 gene cluster." (PMID 29416783, 2018). "A previous study showed that single-nucleotide polymorphisms in CHRNA5 and CHRNA3 were associated with nicotine dependence." (PMID 29207642, 2017). "Cluster of two genes CHRNA5 and CHRNA3 on the chromosome 15q25 region, which encodes neuronal nicotinic acetylcholine receptor subunits, is associated with nicotine dependence and smoking quantity." (PMID 27344179, 2016). "Rare missense variants in CHRNB4 (T375I and T91I) and in CHRNA3 (R37H) are associated with lower risk for nicotine dependence and fewer cigarettes per day." (PMID 24478678, 2014). "Genetic variants in CHRNA3/5 (rs8034191 and rs1051730) were significantly associated with nicotine dependence." (PMID 21232152, 2011). "Genotypes for two SNPs in the CHRNA3/5 region (rs8034191, rs1051730) previously associated with nicotine dependence and COPD were analyzed for association to COPD and nicotine dependence phenotypes." (PMID 21232152, 2011). "Genome-wide association studies implicate variations in CHRNA5 and CHRNA3 as being associated with nicotine addiction (NA)." (PMID 21858091, 2011). "These trends, while not statistically significant (p ≈ 0.06–0.10), are consistent with the hypothesis that CHRNA3/5 variants may contribute to increased nicotine consumption and nicotine dependence severity." (PMID 41301874, 2025). "Evidence indicates that allelic variations in the CHRNA3 gene, which encodes the α3 subunit, are associated with an elevated risk of nicotine addiction, although the precise mechanisms remain unclear." (PMID 41179996, 2025). "Additionally, rs3743075 in CHRNA3 was significantly associated with the Fagerström Test for Nicotine Dependence score." (PMID 40072291, 2025). "This trend supports a possible role of CHRNA3 variants in nicotine dependence." (PMID 41301874, 2025). "Chrna3 is part of a locus on chromosome 15q25 with Chrna5 and Chrnb4, which has also been identified in human GWASs to be associated with smoking-related behaviors and nicotine dependence." (PMID 37295945, 2023). "Hartz and colleagues, focusing on the nicotinic receptor subunit genes associated with nicotine dependence (CHRNA5/CHRNA3/CHRNB4 on chromosome 15q25 and CHRNB3/CHRNA6 on chromosome 8p11) investigated the relationship between nicotine dependence and bipolar disorder." (PMID 35893041, 2022).
nicotine dependence (continued). "CHRNA3 rs578776 polymorphism was reported to be associated with change in nAChR functioning, and with nicotine dependence levels, while such associations could not be shown by some other studies." (PMID 35222535, 2022). "The adverse effects on lifespan of the two associated loci have both likely been hidden from natural selection, CHRNA3/5 because its effect is mediated through the modern risk of nicotine dependence and APOE, because its effect occurs long after child-bearing age." (PMID 27029810, 2016). "Our results suggest that the CHRNA3 rs578776 T allele’s protective effect against smoking dependence may be due to its association with normal reward sensitivity to intrinsically pleasant activity in smokers." (PMID 24065931, 2013). "Therefore, our findings support a potential association between CHRNA3/5 variants and higher tobacco intake, suggesting that these polymorphisms may contribute to genetic susceptibility to smoking nicotine dependence." (PMID 41301874, 2025). "In parallel, nicotinic acetylcholine receptor (nAChR) genes located in the CHRNA3/CHRNA5/CHRNB4 cluster on chromosome 15q25.1 have been consistently linked to smoking behavior, nicotine dependence, and COPD risk." (PMID 41301874, 2025). "Among the genetic determinants, polymorphisms in the CHRNA3/5 and EPHX1 genes have been implicated in nicotine dependence and susceptibility to COPD in several populations." (PMID 41301874, 2025). "We found genes related to nicotine addiction (CHRNA3, CHRNA4, CHRNA5), neurodegeneration (IREB2), chromosome maintenance (HIST1H2BD), mRNA stability (CSDC2), and transcriptional repression to be potentially affected by the pregnancy maternal smoking phenotype." (PMID 40074595, 2025). "The associations have been found between the rs1051730 A allele of CHRNA3/the rs16969968 A allele of CHRNA5 and nicotine dependence." (PMID 37906564, 2023). "The gene cluster region, CHRNA3/CHRNA5/CHRNB4, encoding for nicotinic acetylcholine receptor (nAChR) subunits, contains several genetic variants linked to nicotine addiction and brain disorders." (PMID 34206324, 2021). "Several well-known nicotine-addiction-associated genes, including CHRNA5, PSMA4, and CHRNA3, were identified and their cross-brain-tissue-association patterns were revealed." (PMID 35052378, 2021). "The CHRNA3-CHRNA5-CHRNB4 loci (chr15-q25.1) is the hotspot for genetic variants that are associated with heavy smoking and nicotine dependence." (PMID 28583088, 2017). "The top two CHRNA3 SNPs (rs1051730 and rs12914385, r2 = 0.93) associated with lung ADC risk also had significant indirect effects through nicotine dependence (a coefficient, p = 0.002 and 0.005, respectively)." (PMID 25233467, 2014). "We investigated six variants known to influence nicotine addiction or alcohol metabolism, including rs16969968 (CHRNA5), rs578776 (CHRNA3), rs1229984 (ADH1B), rs698 (ADH1C), rs1573496 (ADH7), and rs4767364 (ALDH2)." (PMID 24505444, 2014). "Most of the SNPs in CHRNA3 had a significant indirect effect on lung ADC through nicotine dependence." (PMID 25233467, 2014). "Our findings suggest that nicotine dependence plays an important role between genetic variants in the CHRNA5/A3/B4 region, especially CHRNA3, and lung adenocarcinoma." (PMID 25233467, 2014). "Sequencing of the neuronal nicotinic receptor genes in cohorts of nicotine dependent cases and controls has also found associations between variants in three nicotinic receptor genes, CHRNA3, CHRNA4 and CHRNB4, with the risk for nicotine dependence." (PMID 24804708, 2014). "Our finding that the protective T allele of the CHRNA3 rs578776 polymorphism is associated with IRS+ smokers is consistent with previous findings concerning the relationship between that allele and nicotine dependence." (PMID 24065931, 2013).